CCL11 (C-C motif chemokine ligand 11)
Diseases named in the same sentence as CCL11 in open-access papers (continued):
Sharing a sentence is not in itself a finding about the gene and the disease.
atherosclerosis (17 papers, 2011 to 2025). A disease characterized by the build-up of fatty material and calcium deposition in the arterial wall resulting in partial or complete occlusion of the arterial lumen. "To date, many researchers have chosen CCL11 as one of thecharacteristic biomarkers of atherosclerosis and developed a risk assessmentmodel based on the concentrations of a series of cytokines and chemokines,including CCL11." (PMID 40026499, 2025). "In both heavy smokers and patients with CAD the increase in TREM1 and CCL11 was also found, indicating that an increase in these proteins may be potential risk factors for atherosclerosis development." (PMID 36189218, 2022). "Eotaxin (CCL11) is a chemotactic cytokine produced by epithelial cells, endothelial cells, fibroblasts, and monocytes and has previously been reported to be associated with eosinophil-associated gastrointestinal diseases, allergic asthma, pulmonary fibrosis and atherosclerosis." (PMID 36358697, 2022). "CCL11, known for its role in neurodegenerative diseases by promotingneuroinflammation and oxidative damage, is also critical in vascular inflammationand atherosclerosis." (PMID 40026499, 2025). "These lines have demonstrated thatelevated CCL11 correlates with impaired angiogenesis and endothelial dysfunction,which are critical to atherosclerosis and other cardiovascular diseases." (PMID 40026499, 2025). "CCL11/eotaxin-1 is expressed at high levels at sites of vascular pathology and has been extensively studied in relation to cardiovascular events, including atherosclerosis and CAD." (PMID 39201047, 2024). "CCL11 is highly expressed in SMC-rich area of the atherosclerosis plaque and injured arteries, suggesting that it plays an important role in regulating SMC migration." (PMID 38906863, 2024). "The alteration of A23T in eotoxin or CCL11 does not change the 3D structure of its encoded protein, but it causes the risk of allergic disorders or atherosclerosis." (PMID 31673266, 2019). "Overexpression of the CCL11 and CCR3 genes has beendemonstrated in human atherosclerosis." (PMID 40026499, 2025). "Besides, the levels of CCL11 and its main receptor CC motif receptor 3 (CCR3) are upregulated in human atherosclerosis, suggesting that CCL11 participates in vascular inflammation." (PMID 38906863, 2024). "Moreover, increased expression of CCL11 (eotaxin) and CCR3 receptors is found in human atherosclerosis." (PMID 32330120, 2020). "In our study, we mainly demonstrated that YB1 dephosphorylation attenuated atherosclerosis in vivo, and YB1 dephosphorylation decreased CCLs (CCL2, CCL7, CCL11, CCL12) expressions in VSMCs in vitro, which may be a critical determinant of the reduction in atherosclerotic plaques." (PMID 35990936, 2022).
depression (17 papers, 2015 to 2025). "CCL5, CCL2, and CCL11 were significantly associated with anxiety and depression in a study on the uterine–chemokine–brain axis." (PMID 36614020, 2022). "Later we found similar results in an independent cohort of patients with major depression, indicating that increased serum levels of eotaxin-1/CCL11 were particularly associated with suicidal ideation." (PMID 29962972, 2018). "However, the presence of both bipolar and major depression disorders was associated with higher concentrations of CCL11 in contrast to our clinical data." (PMID 28149283, 2016). "For example, the relevance of the chemokine CCL11 to hippocampal neurobiology in aging may be more relevant to AD and the second peak of depression incidence in older age – both of which are associated with hippocampal pathology." (PMID 26441528, 2015). "Elevated concentrations of CCL11 have been associated with psychiatric disorders and ROS/RNS-induced oxidative stress, which represents a factor in promoting major depressive disorder and phenotypic switching." (PMID 38674602, 2024). "Taken together, these findings implicate CCL11 as a key player in the systemic immune influence on hippocampal function – with great relevance to psychiatric disorders, particularly depressive disorders and AD." (PMID 26441528, 2015). "However, later research comparing cytokine and chemokine profiles in depression and dysthymia reported elevated CCL11 in connection with other cytokines creating a specific network architecture in dysthymia." (PMID 36614020, 2022). "Positive correlations were observed between MIP-1α/CCL3, MIP-1β/CCL4, MCP-1/CCL2, MIP-3α/CCL20, RANTES/CCL5, Eotaxin/CCL11, and I-TAC/CXCL11 with high scores for anxiety (HARS) (p < 0.05) and for depression (HDRS) (p < 0.004)." (PMID 34863117, 2021). "The aim of this study was to test the relationship between depression and plasma concentrations of CCL2, CCL11, CX3CL1 and CXCL12 in mildly and moderately depressed primary-care patients, as well as the potential influence of an effective iCBT intervention on those molecules." (PMID 31974503, 2020). "This meta-analysis indicates that a number of these chemokines (CCL2, CCL3, CCL4, CCL11, CXCL4, CXCL7 and CXCL8) when measured in the blood discriminate between those with and without depression." (PMID 29133955, 2018).
ovarian carcinoma (16 papers, 2010 to 2025). A malignant neoplasm originating from the surface ovarian epithelium. "It has been reported that CCL5-induced invasion of ovarian cancer stem-like cells is mediated by CCR1 and CCR3, and CCR3, along with CCR2 and CCR5, are associated with CCL11-stimulated proliferation, migration, and invasion of ovarian cancer cells." (PMID 34206004, 2021). "Their findings reveal that CCL11 potently enhances malignant behaviors in ovarian carcinoma cell lines via effects that are effectively abrogated by receptor-specific neutralizing antibodies." (PMID 40429807, 2025). "Clinically, ovarian cancer patients exhibit significantly reduced serum CCL11 levels compared to healthy controls and patients with other malignancies, with these levels inversely correlating with relapse-free survival post resection." (PMID 40429807, 2025). "Emerging evidence indicates that CCL11 production is not limited to stromal cells but is also exhibited by tumor cells in various malignancies, including ovarian cancer, hepatocellular carcinoma, and colorectal cancer." (PMID 40429807, 2025). "CCL11 promoted ovarian cancer growth and metastasis by stimulating the proliferation and migration of ovarian carcinoma cell lines." (PMID 36110847, 2022). "In particular, the role of CCL11/eotaxin-1 in proliferation and invasion of ovarian cancer cells was analyzed." (PMID 20049170, 2010). "Importantly, therapeutic intervention through CCL11 axis blockade using neutralizing antibodies significantly enhances cisplatin sensitivity in ovarian carcinoma cells, suggesting promising combination therapy strategies." (PMID 40429807, 2025). "The list of ovarian cancer-promoting agents upregulated in DIPS cells includes mediators of cancer cell proliferation (CCL11 – also via STAT3), migration (TGF-β1), invasion (PDGF-D, TGF-β1), epithelial-mesenchymal transition (TGF-β1, TSP-1), and angiogenesis (ANG-1)." (PMID 34674640, 2021). "The chemokine CCL11, acting as selective eosinophil chemo-attractant, was found to be derived from fibroblast and tumor cells, and could be highly expressed in ovarian cancer and prostate cancer." (PMID 31803620, 2019). "In ovarian cancer, it has been reported that monoclonal antibodies or pharmacological inhibitors targeting CCL11 may be beneficial for the treatment of the disease." (PMID 31620367, 2019). "In fact, CCL11/CCR3 have been implicated as diagnostic biomarkers in gastric cancer, prostate cancer, and ovarian cancer, and as prognostic biomarkers in renal cell carcinoma, lymphoma and ovarian cancer." (PMID 27119233, 2016). "CCL11 is one of several chemokine genes that are overexpressed in ovarian carcinoma." (PMID 26949191, 2016). "Together, these data suggest that CCR3 in human ovarian cancer cells can be stimulated by CCL7 from TAMs, as well as CCL5 and CCL11, and can play a critical role in ovarian cancer metastasis." (PMID 34206004, 2021). "Several studies have confirmed this observation - they found sensitivity to be greater than in either marker used alone: MMP-7, CCL18 (CC chemokine 18), CCL11 (CC chemokine 11) and CA125 in ovarian cancer (SE in the early stages 94.4%)." (PMID 28662671, 2017). "CCL11 is a cytokine that induces MEK-1, ERK1/2, and STAT3 phosphoproteins as a mechanism for conferring anti-apoptotic and cisplatin-resistance potential in ovarian carcinoma." (PMID 36528667, 2022).
allergic rhinitis (15 papers, 2017 to 2025). Inflammation of the nasal mucous membranes caused by an IgE-mediated response to external allergens. "CCL11/Eotaxin elevates in various inflammatory diseases with eosinophilic infiltration, such as allergic asthma, allergic rhinitis, and atopic dermatitis." (PMID 36142703, 2022). "To test this, we intravenously treated LinOVA mice with a mixture of anti-IL-5 antibody and anti-CCL11 antibody and induced allergic rhinitis in the model." (PMID 31766714, 2019). "For eotaxin chemokines, CCL11 and CCL24 levels were increased in asthma and allergic rhinitis, and CCL26 levels were increased in allergic rhinitis and atopic skin inflammation." (PMID 33317619, 2020). "Studies using rat models of nasal mucosa of allergic rhinitis (AR) showed that intranasal administration of β-GA downregulates AQP1 together with that of eotaxin 1 (CCL11) and eosinophil (EOS) in nasal mucosa of allergic rhinitis rats and cast effects on inhibiting the progress of AR." (PMID 29721498, 2018).
allergic asthma (14 papers, 2006 to 2025). A asthma with a basis in a pathological type I hypersensitivity reaction. "In allergic asthma, Cloots and coworkers showed that mice genetically deficient for Arg1 displayed a reduction in Il4, Il5, Il13, Ccl2, and Ccl11, all Th2-related genes, suggesting that Arg1 may regulate type 2 inflammation." (PMID 34834178, 2021). "Herjan and colleagues have shown that the IL17A treatment of airway smooth muscle cells can reduce CCL11 expression in a mouse model of allergic asthma." (PMID 39108259, 2024). "In asthmatic patients and OVA-sensitized mice, macrophages are polarized towards an M2 phentoype, suggesting that these cells are an important source of CCL11 during allergic asthma." (PMID 36324676, 2022). "In a mouse model, IL-13 is an important mediator of allergic asthma and induces IL-5 and eotaxin/CCL11 dependent eosinophil recruitment into the airways." (PMID 33265990, 2020). "CCL11/eotaxin has been shown to be a potent eosinophil chemotactic mediator and is believed to be important in the development of allergic asthma and is a major eosinophil chemoattractant in our model." (PMID 17044927, 2006). "House dust extracted in PBS and shown to contain high levels of cockroach allergens results in pulmonary inflammation, AHR and increased levels of lung CCL11, and plasma IgE in a mouse model of allergic asthma." (PMID 17044927, 2006). "We extracted total RNA from the lung tissue of mice from both the control and the F2-administered groups in the allergic asthma model and examined the changes in the Th2 cytokines IL-4, IL-5, and IL-13, eosinophil-recruiting chemokine CCL11 and allergic asthma-related cytokine IL-33 using RT-qPCR." (PMID 34576124, 2021).
atopic dermatitis (14 papers, 2014 to 2025). "Eotaxin-1/CCL11 is an important biomarker of atopic dermatitis involved in the selective recruitment of eosinophils into inflammatory foci, thereby being an important participant in allergic and atopic reactions." (PMID 39457662, 2024). "CCL11 is upregulated in atopic dermatitis while CCL7 is increased in psoriasis and sclerosis where they are thought to promote skin inflammation and fibrosis." (PMID 37228128, 2023). "Given the report that SNP rs111568837 in the promoter of CCL11 correlated with the incidence of atopic dermatitis in an Italian cohort, we investigated whether rs111568837 also was associated with FM." (PMID 29927949, 2018). "Eotaxin (CCL11), a Type-2 chemokine, is a potent chemoattractant and activator of CC chemokine receptor-3 (CCR3)-expressing eosinophils that accumulate in high numbers in the lungs of asthmatic patients as well as in the lesional skin from atopic dermatitis patients." (PMID 29933387, 2018). "Interestingly, the CCL11 coding SNP rs1129844 that was significant in our cohort was not statistically significant in the Italian atopic dermatitis cohort." (PMID 29927949, 2018).
cognitive decline (14 papers, 2016 to 2025). "Elevated CCL11 in the plasma and cerebrospinal fluid seen in aging mice and humans are associated with declining neurogenesis, neurodegenerative disease, and cognitive decline and may contribute to driving neovascularisation in AMD via interaction with CCR3." (PMID 35501923, 2022). "In ongoing studies we are investigating whether there is a causal link between increased CCL11 and synaptic pruning by microglia, but we hypothesize that CCL11 promotes cognitive decline by directly targeting microglia (the brain cells expressing the highest levels of its main receptor, CCR327)." (PMID 30820468, 2019). "Some of these factors, notably CCL11, B2M, and transforming growth factor-β1 (TGF-β1), have been causally linked to decreased neurogenesis and cognitive decline in young mice subjected to heterochronic parabiosis." (PMID 40407975, 2025). "MIP1A/CCL3 and eotaxin/CCL11 are linked to AD, MCP1/CCL2 levels correlate with neuroinflammation, brain atrophy, and cognitive decline in AD, and MCP3/CCL7 is part of a diagnostic panel for AD." (PMID 39574895, 2024). "Increased expression of CCR3 and its ligands (CCL5, CCL11, and CCL24) are also associated with cognitive decline associated with aging." (PMID 38332938, 2024). "However, recent studies have identified CCL11 as a significant factor in the aging process, particularly in the context of neuroinflammation and cognitive decline." (PMID 40407975, 2025). "For example, the chemokine CCL11 (eotaxin-1), which is elevated in the cerebrospinal fluid (CSF) of Long COVID patients, inhibits neurogenesis and oligodendrocyte function, further promoting cognitive decline." (PMID 40507911, 2025). "CCL11 transport across the blood-brain barrier (BBB) resulted in region-specific alterations of eotaxin brain levels and age-related increases in humans have been implicated in cognitive decline in a novel mouse model." (PMID 27737716, 2016). "Although levels of CCL- 11 (eotaxin- 1), a chemokine linked to aging and cognitive decline, are not elevated in PD patients, studies using murine models of PD have demonstrated that neutralizing systemic levels of CCL- 11 and CCL- 5 can protect the nigrostriatal pathway from neurodegeneration." (PMID 40407975, 2025). "CCL11 rapidly crosses the blood–brain barrier (BBB), suggesting that blood-borne CCL11 may directly affect the brain and cognitive decline." (PMID 36982260, 2023).
colorectal cancer (14 papers, 2007 to 2024). A primary or metastatic malignant neoplasm that affects the colon or rectum. "The chemokine encoded by the CCL11 gene displays the chemotactic activity of eosinophils and shows anti-cancer characteristics in colorectal carcinoma." (PMID 35603163, 2022). "In addition, differential expression of genes linked to intestinal bowel disease (i.e. Ccr3, Ccl11 and Tnfr) and colorectal cancer development (i.e. Wt1 and Mmp25) was observed between males and females." (PMID 25243059, 2014). "Studies have shown that Eotaxin-1 and its receptors are significantly upregulated in colorectal cancer, especially CCL11 and CCR3 (the receptor for CCL11)." (PMID 39399504, 2024). "Recently, CCL11 expression detected in gastrointestinal punch biopsies of colorectal cancer (CRC) patients was shown to correlate with eosinophil infiltration into tumor nodules." (PMID 35756626, 2022). "We performed a comprehensive literature search using the MEDLINE/PubMed electronic database on 24 February 2020, with the following search strategy: “CCL11/CCL24/CCL26/CCR3 AND colorectal cancer”." (PMID 32481530, 2020). "The concentrations of other parameters (CCL11, CCL26, CXCL14 and CA 19-9) were comparable to or even lower in the sera of patients with colorectal cancer compared to the group of healthy volunteers." (PMID 37240636, 2023). "Moreover, CCL11 may also regulate eosinophil migration in the tumor microenvironment through its interaction with CCR3, and its significant role has been confirmed in colorectal cancer, Hodgkin lymphoma, and oral squamous cell carcinoma." (PMID 38459592, 2024).
Obesity (14 papers, 2015 to 2025). Accumulation of substantial excess body fat. "Although CCL11 has been demonstrated to be increased in patients with diabetes and obesity, further research is needed to establish the role of CCL11 in diabetic neuropathy and obesity-induced hypersensitivity." (PMID 39457105, 2024). "Elevated plasma levels of MCP-1 and CCL-11 have been also reported in neurodegenerative diseases suggesting that HFD induced obesity can trigger EAE severity though induction of proinflammatory MCP-1 and chemokines such as CCL-11." (PMID 36164343, 2022). "Conversely, the abundance of the chemoattractant CCL11 in hASC‐CM was lower in a background of obesity only, and increased markedly in the hASC‐CM of the OE group." (PMID 35811457, 2022). "Notably, increased adipose tissue levels of multiple β-chemokines (CCL2, CCL3, CCL5, CCL7, CCL8, CCL11) and chemokine receptors (CCR1, CCR2, CCR3, CCR5) have been linked with obesity and associated metabolic inflammation." (PMID 28396851, 2017). "In humans, cytokine profiles in the blood can be reversed after bariatric surgery—elevated CCL14, soluble vascular endothelial growth factor receptor 2 (VEGFR2), and platelet-derived growth factor BB in obesity are reduced, and lower CXCL12, CCL11, and CCL27 in obesity are increased." (PMID 38037591, 2023). "Instead, CCL2 (MCP-1), CCL11 (eotaxin), G-CSF, and CCL4 (MIP-1β) were decreased by exercise regardless of obesity status." (PMID 26110868, 2015).
inflammatory bowel disease (12 papers, 2016 to 2025). A spectrum of small and large bowel inflammatory diseases of unknown etiology. "Bertilimumab, a humanized monoclonal antibody against CCL11, is currently in clinical trials for treating severe allergic disorders and inflammatory bowel disease." (PMID 34795678, 2021). "Bertilimumab, a humanized monoclonal antibody against CCL11, is currently in clinical trials for treating severe allergic disorder, vernal keratoconjunctivitis, and inflammatory bowel disease." (PMID 27119233, 2016). "Another notable results from the MSEA found microbes with differential abundance in Crohn’s disease are enriched for microbes associated with ATG16L1, CCL11 and FUT2, all of which have been implicated in the pathology of Crohn’s diseases, an inflammatory bowel disease (IBD)." (PMID 33293650, 2020).